BEX5 (brain expressed X-linked 5)
Synonyms: NGFRAP1L1
Tractability: PROTAC: UniProt records ubiquitination sites on it; ubiquitination databases record sites on it.
Gene: Protein-coding gene on chromosome X (102,153,464 to 102,156,017, reverse strand). Ensembl gene ENSG00000184515.
Subcellular location: Cytoplasm
Gene Ontology:
Molecular function: protein binding; signaling receptor binding
Biological process: signal transduction
Cellular component: cytoplasm
Homologues: Orthologues: chimpanzee BEX5 (99% identical), macaque BEX5 (85% identical), dog BEX5 (79% identical), pig BEX5 (79% identical), rabbit BEX5 (77% identical). Paralogues in human: BEX3 (55% identical), BEX1 (43% identical), BEX2 (42% identical).
Diseases named in the same sentence as BEX5 in open-access papers:
BEX5 is named in the same sentence as 5 diseases in open-access papers, as found by Europe PMC text mining. Sharing a sentence is not in itself a finding about the gene and the disease. The quoted sentences say what the papers report.
leukoplakia (1 paper, 2016). A white patch or plaque on a mucous membrane that cannot be characterized clinically or pathologically as any other disease. "The correlation of low BEX4 expression with poor cancer-free survival in leukoplakia patients was more significant than other BEX family members including BEX1, BEX2, NGFRAP1 (BEX3) and BEX5." (PMID 27297407, 2016).
cancer (3 papers, 2016 to 2021). A tumor composed of atypical neoplastic, often pleomorphic cells that invade other tissues. "Expression of BEX1, BEX2, BEX4, and BEX5 were found to be reduced in different human cancers." (PMID 28083995, 2017).
tumor (3 papers, 2021 to 2024). "BEX5, a member of the BEX family, is involved in various biological functions related to normal and tumor tissues." (PMID 35273597, 2022). "Despite their contributions to tumor progression, the expression of three genes was not shown to be differentially expressed with radiotherapy (1.049-fold in BEX2, 1.057-fold in BEX3, and 1.064-fold in BEX5) in the microarray results." (PMID 34576008, 2021).
BEX5 also shares sentences with these, for which no sentence is quoted: multiple myeloma (1 paper); myeloid neoplasm (1).